MXI1 (MAX interactor 1, dimerization protein)
Diseases named in the same sentence as MXI1 in open-access papers (continued):
Sharing a sentence is not in itself a finding about the gene and the disease.
lung carcinoma (8 papers, 2020 to 2025). "Mxi1 was poorly expressed in lung cancer tissues and cells and its poor expression was associated with poor prognosis." (PMID 35501353, 2022). "We then divided lung cancer patients into two groups (low and high-risk groups) based on the expression of Mxi1." (PMID 35501353, 2022). "The purpose of the current study was to define the role of MAX interactor 1 (Mxi1) in the pathogenesis of lung cancer and its underlying molecular mechanism." (PMID 35501353, 2022). "To further explore how Mxi1-regulated miR-300 was associated with the lung cancer pathogenesis, we analyzed the potential target genes of miR-300, and identified KLF9, which has been reported to be a tumor suppressor." (PMID 35501353, 2022). "Our previous study has shown that Mxi1 is downregulated and associated with adverse clinical outcomes in lung cancer patients." (PMID 32901121, 2021). "Importantly, it has also been demonstrated that Mxi1 deficiency exacerbates lung cancer progression." (PMID 35501353, 2022). "This study, for the first time, uncovers the underlying mechanism by which Mxi1 suppresses lung cancer progression, imparting an improved understanding of the pathogenesis of lung cancer and providing novel potential therapeutic targets for lung cancer treatment." (PMID 35501353, 2022). "Immunohistochemistry revealed an inverse correlation between UBE2O (high) and Mxi1 (low) expression in lung cancer tissues, consolidating their functional antagonism." (PMID 40426910, 2025). "In lung cancer, UBE2O enhances tumor radioresistance by degrading Mxi1 and is associated with poor prognosis." (PMID 40426910, 2025). "In this study, we have endeavored to define the roles of Mxi1 and Mxi1-regulated miR-300 in the initiation/progression of lung cancer using in vitro and in vivo approaches." (PMID 35501353, 2022). "The results showed that Mxi1 overexpression resulted in reduced wound closure and lung cancer cell invasion." (PMID 35501353, 2022). "The role of Mxi1 in regulating the mobility of lung cancer cells was also examined by scratch and Transwell assays." (PMID 35501353, 2022). "According to the results of Kaplan-Meier survival analysis, low Mxi1 expression was significantly related with a dismal overall survival rate among lung cancer patients." (PMID 35501353, 2022). "As reflected by fluorescence-activated cell sorting (FACS), upregulated Mxi1 significantly reduced the viability of lung cancer cells." (PMID 35501353, 2022). "UBE2O targets Mxi1 for ubiquitination and degradation to promote lung cancer progression and radioresistance." (PMID 36185617, 2022). "Collectively, these findings suggest that Mxi1 can inhibit lung cancer progression by regulating the miR-300/KLF9 axis and GADD34-mediated immunosuppression." (PMID 35501353, 2022). "Mxi1 or KLF9 elevation or miR-300 repression inhibited lung cancer cell proliferation, as evidenced by reduced Ki67 and PCNA expression, and lowered invasion and migration." (PMID 35501353, 2022). "It has been well documented that Mxi1 serves as a negative regulator of Myc and exerts inhibitory action on different malignancies, including lung cancer." (PMID 35501353, 2022). "Mechanistically, we have revealed that Mxi1 exerts an inhibitory effect on lung cancer progression via the miR-300/KLF9/GADD34 axis." (PMID 35501353, 2022). "To define the role of Mxi1 in tumor progression, we altered the expression of Mxi1 in lung cancer cells (A549 and HCC827) and validated the transfection efficiency by RT-qPCR." (PMID 35501353, 2022). "It has been well documented that Mxi1 serves as a negative regulator of Myc and exerts an inhibitory effect on lung cancer and other types of malignancy." (PMID 35501353, 2022). "In this study, we have defined the molecular mechanism by which Mxi1 regulates lung cancer progression, and shown that Mxi1 was significantly downregulated in lung tumors and the downregulation was associated with poor prognosis." (PMID 35501353, 2022).
lung carcinoma (continued). "We also found that genetical and pharmacological inhibition of UBE2O impair tumorigenesis and radioresistance in a Mxi1-dependent manner in lung cancer." (PMID 32901121, 2021). "Our previous study has clearly shown that Mxi1 is downregulated and inhibits lung cancer cell proliferation." (PMID 32901121, 2021). "Clinically, UBE2O is remarkedly upregulated and negatively correlated with Mxi1 downregulation in lung cancer tissues." (PMID 32901121, 2021). "Collectively, our results indicate that UBE2O promotes cell proliferation and radioresistance via its ability to degrade Mxi1 in lung cancer cells." (PMID 32901121, 2021). "We have previously found that overexpression of Mxi1 enhanced the radiosensitivity in lung cancer cells." (PMID 32901121, 2021). "In this study, we demonstrate that UBE2O targets Mxi1 for ubiquitination and degradation, which is a new mechanism for Mxi1 regulation in lung cancer." (PMID 32901121, 2021). "Our clinical data clearly show that UBE2O protein is overproduced and inversely correlated with Mxi1 expression in lung cancer." (PMID 32901121, 2021). "Endogenous UBE2O bound Mxi1 in two lung cancer cell lines (H1299, A549)." (PMID 40426910, 2025). "In addition, a tumor suppressor negatively regulating MYC function in lung cancer, MXI1, was also identified in the selection." (PMID 37251921, 2023). "However, the E3 ubiquitin ligase β-Trcp ubiquitinates and reduces Mxi1 protein levels, which leads to radioresistance in lung cancer." (PMID 38137461, 2023). "In lung cancer tissues, Mxi1 exerts a negative regulatory influence on the oncogene Myc." (PMID 38137461, 2023). "Our data have demonstrated that Mxi1 overexpression impairs lung cancer cell malignant potentials." (PMID 35501353, 2022). "Moreover, in this study, we defined that Mxi1 negatively regulated the expression of miR-300 in lung cancer based on results of our bioinformatics analysis." (PMID 35501353, 2022). "As expected, Mxi1 was poorly expressed in lung cancer cell lines." (PMID 35501353, 2022). "Cumulatively, Mxi1 could arrest malignant features of lung cancer cells by regulating the miR-300/KLF9 axis." (PMID 35501353, 2022). "Furthermore, tumor suppressor roles of Mxi1 have been validated in different types of cancers, including prostate cancer, glioblastoma, and lung cancer." (PMID 35501353, 2022). "Our study not only confirmed their findings but also furthered our understanding of the role of Mxi1 in the pathogenesis of lung cancer, by demonstrating that Mxi1 elevation inhibited tumor cell proliferation as evidenced by reduced Ki67 and PCNA levels, and lower invasion and migration." (PMID 35501353, 2022). "Taken together, these data demonstrate that UBE2O overproduction may lead to Mxi1 downregulation and predict adverse prognosis in lung cancer patients." (PMID 32901121, 2021). "Notably, inactivation of UBE2O with ATO dramatically upregulated the protein levels of Mxi1 and enhanced radiosensitivity in lung cancer, suggesting that ATO exerts radiosensitization effect via the inhibition of the UBE2O-Mxi1 axis." (PMID 32901121, 2021). "Besides, we also found that Mxi1 is downregulated and leads to enhanced radiosensitivity in lung cancer." (PMID 32901121, 2021). "Furthermore, our rescue experiments showed that the inhibiting effects of UBE2O depletion on the proliferation and radioresistance of lung cancer cells can be restored by Mxi1 knockdown." (PMID 32901121, 2021). "UBE2O could mediate Mxi1 ubiquitination and then promote lung cancer progression and radioresistance." (PMID 34976998, 2021). "Considering that UBE2O negatively controls the abundance of Mxi1 at translational level, our results strongly suggest that UBE2O overexpression may result in the downregulation of Mxi1 in lung cancer." (PMID 32901121, 2021). "Moreover, genetical and pharmacological inhibition of UBE2O impairs tumorigenesis and radioresistance in a Mxi1-dependent manner in lung cancer in vitro and in vivo." (PMID 32901121, 2021).
lung carcinoma (continued). "Moreover, we demonstrate that UBE2O is overexpressed and negatively correlated with Mxi1 protein levels in lung cancer tissues." (PMID 32901121, 2021). "Since UBE2O controls the accumulation of Mxi1, we next investigated whether UBE2O is associated with radiosensitivity of lung cancer." (PMID 32901121, 2021). "Furthermore, we show that genetical or pharmacological blockade of UBE2O impairs tumor progression and radioresistance in lung cancer in vitro and in vivo, and these effects can be restored by Mxi1 inhibition." (PMID 32901121, 2021). "Since Mxi1 is a ubiquitination substrate of UBE2O, we determined whether Mxi1 is required for the functions of UBE2O in lung cancer." (PMID 32901121, 2021). "One possible target could be Max interactor (Mxi1) known to promote Myc activation and radioresistance in lung cancer cells." (PMID 32483461, 2020). "We proposed a hypothesis that Mxi1 played a suppressive role in MDSC-mediated immunosuppression in lung cancer progression by modulation of miR-300, which consequently regulates the activity of Kruppel-like factor 9 (KLF9)/growth arrest and DNA damage-inducible protein (GADD34) axis." (PMID 35501353, 2022). "However, our understanding of Mxi1 in lung cancer remains incomplete." (PMID 35501353, 2022). "Furthermore, UBE2O overexpression predicts poor clinical outcomes and correlates with Mxi1 downregulation in lung cancer tissues, indicating that targeting the UBE2O/Mxi1 axis may be an attractive therapeutic strategy for treating lung cancer." (PMID 32901121, 2021). "In lung cancer, ATO treatment significantly increases Mxi1 protein levels in a concentration- and time-dependent manner." (PMID 40426910, 2025). "Collectively, our work reveals that UBE2O facilitates tumorigenesis and radioresistance by promoting Mxi1 ubiquitination and degradation, suggesting that UBE2O is an attractive radiosensitization target for the treatment of lung cancer." (PMID 32901121, 2021). "We also determined the expression of Mxi1 in lung cancer cell lines (H292, A549, HCC827, H1299, and H1975) and a normal human bronchial epithelial cell line (HBE)." (PMID 35501353, 2022). "Since UBE2O negatively regulates the protein levels of Mxi1, we speculated that UBE2O might be overexpressed in lung cancer." (PMID 32901121, 2021). "The downregulation of Mxi1 expression has been found in human lung cancer, but the mechanisms of Mxi1 downregulation has not been fully understood." (PMID 32901121, 2021).
malignant lymphoma (4 papers, 2013 to 2024). "The significance of MAD in leukemia and lymphoma is poorly understood, but it has been observed that mutations in MAD1 and MXI1 correlated with a poor clinical outcome in acute leukemia." (PMID 23527180, 2013).
renal carcinoma (4 papers, 2017 to 2023). A carcinoma arising from the epithelium of the renal parenchyma or the renal pelvis. "Previous study identified Myc-Mxi1 signaling as a crucial downstream effector of FoxOs in the regulation of proliferation of renal cancer." (PMID 36062157, 2022). "Alternatively, HIF-1 negatively regulates mitochondrial biogenesis and oxygen consumption by inhibiting C-MYC via MXI-1 dependent and MXI-1 independent pathways in renal carcinoma." (PMID 28373964, 2017).
colon carcinoma (3 papers, 2009 to 2020). "This is consistent with recent findings in DLD-1 colon carcinoma cells in which AKT2 silencing resulted in increased FOXO3A activity leading to increased MXI1 RNA expression." (PMID 20604938, 2010).
neuroblastoma (3 papers, 2011 to 2022). Neuroblastoma (NB) is the most common solid, extracranial childhood tumor. "Compared with Mxi1-1, Mxi1-0 has an alternative first exon (exon 0), encoding a different SIN3 interaction domain (SID), and is reported to promote proliferation of various types of cells, such as endothelial cells and neuroblastoma cells." (PMID 35401684, 2022). "Therefore, the impact of the genotype on ODC1 expression in neuroblastoma may depend on the balance of MYCN levels and MAD1/MXI1 levels, and their binding with MAX." (PMID 33918978, 2021).
prostate tumour (3 papers, 1997 to 2020). "The oncogene MXI1 on chromosome band 10q24-25 is mutated in a proportion of prostate tumours and loss of heterozygosity occurs at this site, suggesting the location of a tumour suppressor in this region." (PMID 9376279, 1997).
Insulin resistance (2 papers, 2006 to 2022). Increased resistance towards insulin, that is, diminished effectiveness of insulin in reducing blood glucose levels. "Knockdown of Jund, Max and Mxi1 downregulated Irs2, which suggested that these transcription factors are involved in Irs2 transcription and may contribute to insulin resistance." (PMID 34921686, 2022). "Max interactor protein, MXI1 (gene L07648) competes for MAX thus negatively regulates MYC function and may play a role in insulin resistance." (PMID 17217525, 2006).
osteosarcoma (2 papers, 2021 to 2022). A usually aggressive malignant bone-forming mesenchymal neoplasm, predominantly affecting adolescents and young adults. "Our in vitro experiments demonstrated that silencing MXI1 attenuated proliferation, migration, and invasion of osteosarcoma cells, confirming the important role of MXI1 in osteosarcoma progression." (PMID 35071320, 2021). "Meanwhile, MXI1 up-regulation was in relation to unfavorable survival outcomes of osteosarcoma patients (p < 0.001, HR = 5.91, and 95% CI = 2.48–14.07)." (PMID 35071320, 2021). "In the five-gene signature, we separately evaluated the prognostic potential of CAVIN1, EGFR, SCD3, TES, and MXI1 in osteosarcoma." (PMID 35071320, 2021). "Three genes, including COL13A1, MXI1, andTBRG1, could be used as DNA methylation biomarkers of accurate diagnosis and therapy for osteosarcoma in the future." (PMID 35602303, 2022). "MXI1 is a key transcription factor involved in osteosarcoma progression." (PMID 35071320, 2021). "Our results confirmed that SCD3, EGFR, and MXI1 were remarkably up-regulated while CAVIN1 and TES were prominently down-regulated in U2OS osteosarcoma cells compared with hFOB1.19 normal cells." (PMID 35071320, 2021). "In addition, effects of DNA methylation inhibitors on osteosarcoma cell phenotype and prognosis in animal models targeting the three identified genes (COL13A1, MXI1, and TBRG1) deserve further study." (PMID 35602303, 2022). "Additionally, our experimental results confirmed that SCD3, EGFR, and MXI1 were remarkably up-regulated while CAVIN1 and TES were prominently down-regulated in osteosarcoma cells compared with normal cells." (PMID 35071320, 2021). "The three genes (COL13A1, MXI1, and TBRG1) regulated by DNA methylation were identified to relate with the outcomes of OS patients, which might provide a new insight to the pathological mechanism of osteosarcoma." (PMID 35602303, 2022).
atopic asthma (1 paper, 2015). An asthma that is characterized by symptoms that are triggered by an allergic reaction caused by inhaled allergens such as dust mite allergen, pet dander, pollen and mold. "SMC3 and RAD21 interact with MXI1 (found among ChIP targets with decreased mRNA) to function in the cohesin complex, and the former is associated with atopic asthma." (PMID 26544975, 2015).
Barrett's metaplasia (1 paper, 2008). "The only gene to be significantly altered in Barrett's metaplasia in comparison with normal gastric mucosa was MXI1-0, the alternatively transcribed isoform of MXI1." (PMID 18493233, 2008). "In comparison to matched normal gastric controls the expression of c-MYC and MXI1 was significantly upregulated in Barrett's metaplasia; conversely, the expression of MAD1 was significantly lower in the metaplastic lesion than in the normal mucosa." (PMID 18493233, 2008). "Quantitative real-time RT–PCR was utilised to assess the expression of the mRNAs encoding c-MYC, MAD1, MXI1, MXI1-0 and MAX in normal epithelia, Barrett's metaplasia and oesophageal adenocarcinoma specimens." (PMID 18493233, 2008). "When expression in adenocarcinoma was evaluated in comparison to matched Barrett's metaplasia it was apparent that expression of MYC, MXI1 and MAX were significantly elevated in the malignant transformation of Barrett's metaplasia." (PMID 18493233, 2008). "While a difference in MYC and MXI1 was demonstrated between Barrett's metaplasia and adenocarcinoma at the level of mRNA, there was no significant alteration in protein expression in malignancy." (PMID 18493233, 2008).
brain tumor (1 paper, 2013). "In this study, we found that the expression of MXI1 mRNA in 18 pairs of samples was reduced by >40% in 61% of our brain tumor samples." (PMID 24376632, 2013). "In addition, we found that MXI1 mRNA levels were reduced by >40% in 61% of brain tumors compared to the corresponding normal brain tissues." (PMID 24376632, 2013).
cervical carcinoma (1 paper, 2016). A carcinoma arising from either the exocervical squamous epithelium or the endocervical glandular epithelium. "In the correlation network among RAD21, SMC3, and MXI1, the three factors were tightly connected with one another in HeLa-S3 cervical carcinoma cells." (PMID 27139377, 2016).
depression (1 paper, 2021). "Among the common genes of depression and diabetes, there are four TFs, namely, BCL3, MXI1, GMEB2, NFKB1." (PMID 34833079, 2021).
hepatoma (1 paper, 2011). "In a murine hepatoma cell line Mxi-1 induction by hypoxia was also found to be HIF-1-dependent and caused concomitant downregulation of the c-Myc target genes." (PMID 21925595, 2011).
kidney cancer (1 paper, 2023). Primary or metastatic malignant neoplasm involving the kidney. "MXI1, a member of the Mad family proteins known to antagonize c-MYC-dependent transcription, has a potential oncogenic role in RCC, as MXI1 knockdown impaired kidney cancer xenograft formation in nude mice." (PMID 36973268, 2023).
lung adenocarcinoma (1 paper, 2021). A carcinoma that arises from the lung and is characterized by the presence of malignant glandular epithelial cells. "Importantly, we analyzed the association between UBE2O and Mxi1 expression in the paired lung adenocarcinoma tissues and found that there was a negative correlation between UBE2O and Mxi1 protein levels (P < 0.001)." (PMID 32901121, 2021).
malignant glioma (1 paper, 2002). A grade III or grade IV glioma arising from the central nervous system. "Altogether, our results indicate that Mxi1 mediates the down-regulation of cyclin B1 gene expression in malignant gliomas suggesting that this gene is a functional target of the tumour suppressor activity of Mxi1." (PMID 11875718, 2002).
melanoma (1 paper, 2022). A malignant, usually aggressive tumor composed of atypical, neoplastic melanocytes. "Loss of the MXI1 allele is found in approximately 50% of melanoma cases and occurs more frequently in recurrent or metastatic tumors." (PMID 35602303, 2022).
monocytic leukemia (1 paper, 2022). "Initially isolated using a yeast two-hybrid screen that employed Max as a “bait”, Mxd2 (originally known as Mxi1) is expressed in a variety of tissues and up-regulated in response to the differentiation of U937 monocytic leukemia cells." (PMID 35203395, 2022).
oesophageal adenocarcinoma (1 paper, 2008). "MXI1 immunoreactivity in oesophageal adenocarcinomas was largely moderate in intensity and cytoplasmic in localisation." (PMID 18493233, 2008). "In accordance with the mRNA data c-MYC, MAD1 and MXI1 expression was significantly higher in oesophageal adenocarcinoma than in matched normal gastric controls." (PMID 18493233, 2008).
polycystic kidneys (1 paper, 2015). "Moreover, inactivation of Mxi1 (for Max interactor 1) induces IL-8 secretion activation in polycystic kidneys." (PMID 26508814, 2015).